IL18 (interleukin 18)
Diseases named in the same sentence as IL18 in open-access papers (continued):
Sharing a sentence is not in itself a finding about the gene and the disease.
COVID-19 (continued). "When we probed cytokine (i.e. IL-12 and IL-18)-mediated MAIT cell activation, MAIT cells from COVID-19 patients showed an altered cytokine expression profile characterised by impaired upregulation of IL-17A, TNFα, granzyme B and perforin." (PMID 33546489, 2021). "In our study, the levels of seven cytokines in COVID-19 patients (IL-6, IP-10, IL-8, MIG, MIP-1β, IL-18, TNF-α) were different from those in healthy controls, while M-CSF, MCP-1, FLT-3, VEGF, IL-1RA, EGF, eotaxin and MCP-1 were not different." (PMID 34539644, 2021). "According to recent reports, a similar immunopathologic lesion is described in severe COVID-19 cases, with enriched macrophages in lungs and elevated cytokines such as IFN-γ, IL-1, IL-6, TNF, and IL-18 in blood, accelerating the collapse of immune homeostasis." (PMID 33397398, 2021). "For example, pro-inflammatory cytokines and chemokines CXCL8 (q < 2.0 × 10−16), IL18 (q = 0.009), and IL1B (q < 2.0 × 10−16) were elevated in monocytes from male patients with severe COVID-19 compared to females." (PMID 34330889, 2021). "Compared with severe COVID-19 patients, active AOSD patients had markedly higher levels of IL-18, which is a potential discriminator between active AOSD and severe COVID-19." (PMID 34367188, 2021). "Many of these cytokines, including IL-6, IL-18, IL-33, MCP-1, and MIP-1α, were elevated in the COVID-19 ICU and/or in-hospital mortality groups in our study." (PMID 34960684, 2021). "MAIT cells of COVID-19 patients also had lower expression levels of TNF-alpha, perforin and granzyme B upon stimulation with IL-12 + IL-18." (PMID 34238985, 2021). "A literature search was performed using the databases PubMed, EMBASE, and Web of Science to collect the levels of cytokine including IL-1β, IL-6, IL-18, TNF-α, IL-10, and ferritin in severe COVID-19 patients." (PMID 33552062, 2020). "In conclusion, our findings suggest that both COVID-19 and AOSD have elevated level of ferritin and cytokines, including IL-1β, IL-6, IL-10, IL-18, and TNF-α, indicating systemic inflammation in the pathogenesis of COVID-19 and AOSD." (PMID 33552062, 2020). "Even the higher COVID-19 mortality rate observed in male compared to female patients may correlate with sex differences in the immune responses between male and female, with higher plasma levels cytokines and chemokines including IL-6, IL-8, IL-18, CCL5 found in male patients." (PMID 33362782, 2020). "The present data indicate that DPSC administration might be effective in patients with COVID-19-induced hyper-inflammation, due to the inhibition in the production of several cytokines by activated T lymphocytes, namely, IFNγ, TNFα, IL-2, IL-9, IL-10, IL-17A, IL-18, IL-21, and IL-27." (PMID 33634100, 2020). "It should also be noted that we did not determine the cellular source(s) of IL-18 in patients with acute COVID-19." (PMID 39847442, 2025). "Among the analyzed cytokines, IL-18 emerged as a significant factor, showing a time-dependent increase, particularly in patients who did not experience COVID-19." (PMID 40332340, 2025). "Remarkably, a higher level of circulating IL-18 was found at T3 in comparison to T0 in patients who did not experience COVID-19 after PrEP." (PMID 40332340, 2025). "A key example is COVID-19, where NLRP3 inflammasome activation by SARS-CoV-2 results in massive release of IL-1β and IL-18, leading to cytokine release syndrome, with hyperactivation of myeloid cells and Th17 responses or IL-18-driven IFNγ production and Th1 responses." (PMID 41087719, 2025). "Increased levels of interleukins (IL-1 α, IL-7, IL-17, and IL-18) and chemokines (CCL11, and CXCL1) were found only in the COVID-19-only, whilst PLWH/COVID-19, had increased levels of four different interleukins (IL-5, IL-6, IL-9, and IL-15) and one chemokine (CXCL10) compared to COVID-19-only." (PMID 41516165, 2025).
COVID-19 (continued). "Interestingly, parameters demonstrating an increase in case of moderate/severe COVID-19 (e.g. CRP, APTT, IL-18) negatively correlated with the days elapsed since the positive SARS-CoV-2 test result." (PMID 40303405, 2025). "In pregnant women with acute COVID-19, a significant positive correlation between APTT, TT and a large subset of the tested inflammatory cytokines/chemokines was observed, including IL-6, INF-α2, MCP-1, IL-10, and IL-18." (PMID 40303405, 2025). "In the COVID-19+ group, as expected, significantly increased levels of proinflammatory cytokines/chemokines including INF-α2, INF-γ, MCP-1, IL-6, IL-12p70, IL-17A, IL-18, IL-23 and IL-33 were detected, while the level of IL-10, an anti-inflammatory cytokine was also elevated as compared to controls." (PMID 40303405, 2025). "Our results highlighted an important role of IFNG expressed in lymphoid cells of post-COVID-19 heart tissue, reflected in ISG expression patterns in multiple cell types and states, and identified upregulated IL16 and IL18 expression as hallmarks of post-vaccination myocardial inflammation." (PMID 39994453, 2025). "MAIT cell PD-1 expression at 4 mo after resolution of acute COVID-19 correlated negatively with GzmB expression following IL-12+IL-18 stimulation, a pattern not replicated in the HD group." (PMID 38117799, 2024). "Altogether, our data suggest that blocking IL-1R7 represents a potential therapeutic strategy to specificallymodulate IL-18-mediated hyperinflammation, warranting further investigation of its clinical application intreating IL-18-mediated diseases, including MAS and COVID-19." (PMID 38983847, 2024). "Thus, our results showed that COVID-19 significantly increases the levels of IP-10, HGF, and IL-18 in the plasma of COVID-19 patients compared to healthy and/or recovered individuals." (PMID 38486975, 2024). "Although IL-16 and IL-18 were the only cytokines that were negatively correlated with SOFA scores in patients at different COVID-19 stages, the results were not statistically significant." (PMID 38710800, 2024). "A significantly higher serum IL-18 level was observed in the COVID-19 patients with MAS than in the patients without MAS and the elevated IL-18 level is associated with disease severity and poor clinical outcome in COVID-19 patients." (PMID 38983847, 2024). "As with 24 h cultures, we did not detect any significant changes in IL-18 secretion in either HC or COVID-19 PMNs." (PMID 39172744, 2024). "Another potential candidate for IL-18-blocking therapy is the severe cytokine storm syndrome seen in conditions such as patients undergoing CAR T therapy and in severe cases of COVID-19." (PMID 39769266, 2024). "As expected, performing TPE decreased the amount of anti-type I IFN auto-antibodies and improved the elimination or limited the production of certain inflammatory mediators (IL-18, IL-7, CCL2, CCL3, etc.)circulating in the blood of COVID-19 patients, compared to ST controls." (PMID 39896810, 2024). "Regarding IL18 and CASP1, to the best of our knowledge, a relationship of their polymorphisms with COVID-19 exacerbation has not been previously reported." (PMID 38612539, 2024). "Interrogating expression of individual markers, we found five notable proinflammatory analytes (Caspase-8, EN-RAGE, IL-18, MCP-3, and MMP-1) that were present at higher concentrations in the supernatants of severe COVID-19 patient monocyte cultures compared with healthy monocyte cultures." (PMID 38578283, 2024). "In summary, results from our studies further validated IL-1R7 as a potential therapeutic target and set the stage for a full characterization of the potential of anti-IL-1R7 in clinical studies of IL-18-mediated diseases such as MAS, COVID-19, IBD and rheumatic diseases." (PMID 38983847, 2024). "Elevated IL-6, IL-18 and IL-8 levels have been also described in the serum and CSF of COVID-19 patients in parallel with elevated serum NfL, but not with CSF NfL." (PMID 36769057, 2023).
COVID-19 (continued). "In conclusion, IL-18 is highly expressed in H1N1-induced severe lung injury in mice, and it is an appropriate cytokine to prime hUC-MSCs in vitro to improve precision therapy against viral-induced pneumonia, such as COVID-19." (PMID 36707501, 2023). "Because comparing viral+ and viral− cells did not reveal viral-intrinsic effects on IL1B or IL18 expression, we examined proinflammatory cytokine expression across all clusters in the integrated (COVID-19-infected and control) human BALF data set." (PMID 37737611, 2023). "Our results support the hypothesis that life-threatening COVID-19 may be MAS-like, and may benefit from IL-18 modulation from symptom day 15 onwards." (PMID 36823262, 2023). "The concentrations of the proinflammatory IL-12, IL-18, and IL-23 were not significantly different in COVID-19 patients compared to healthy controls, or between COVID-19 patients before and after one-week therapy." (PMID 37174682, 2023). "However, only the levels of IL-18 and IFN-γ increased, while IL-12 remained unaffected in moderate COVID-19 compared to the control group." (PMID 37373331, 2023). "We, therefore, designed a prospective, longitudinal cohort study to examine IL-18 negative-feedback control in relation to COVID-19 severity and mortality from symptom day 15 onwards." (PMID 36823262, 2023). "The pro-inflammatory cytokines IL-6 and IL-18 were not significantly different in the disease group compared to those in the healthy group, suggesting that acute inflammation subsided while COVID-19 was cured." (PMID 37422499, 2023). "Serum IL-18 levels have previously been shown to negatively correlate with MAIT cell frequencies in various inflammatory diseases such as in multiple sclerosis, and correlates with MAIT cell activation in fatal cases of COVID-19." (PMID 37536148, 2023). "Levels of TNF-α, IL-1Ra, IL-6 and IL-18 were also higher in HD + COVID-19 than in HD patients, without reaching statistical significance." (PMID 36675231, 2023). "Neutralising auto-antibodies to IFN-alpha, seen in life-threatening COVID-19 may explain the elevated levels of fIL-18; IFN-alpha both diminishes IL-18 production from macrophages and is an important inducer of IL-18bp." (PMID 36823262, 2023). "Life-threatening COVID-19 shares clinical similarities with Macrophage Activation Syndrome, which can be driven by elevated Free Interleukin-18 (IL-18) due to failure of negative-feedback release of IL-18 binding protein (IL-18bp)." (PMID 36823262, 2023). "These include interleukin-1 (IL-1), IL-6, IL-18, IL-10, interferon gamma (IFN-γ) and tumor necrosis factor-alpha (TNF-α) secreted by T helper type 1 (TH1) and other cells during the inflammatory process of COVID-19." (PMID 37447302, 2023). "We found that acute COVID-19 neutrophils secreted reduced G-CSF, MIP-1α, MIP-1β, MCP-1, IL-2, SDF-1α, IL-9, IL-17A, IL-18, IL-20 and IL-23 levels, but secreted increased soluble PD1, IP-10 and MIP-2α levels compared to rec-phase and healthy neutrophils upon bacterial challenge." (PMID 35007290, 2022). "Indeed, circulating monocytes in the patient with COVID-19 vaccine-related myopericarditis exhibited upregulated NLRP3 inflammasome expression and IL-18 production." (PMID 35251049, 2022). "NK cells of COVID-19 ICU patients failed to produce IFN-γ upon stimulation with IL-12+IL-18 while those of WARD patients are diminished in their production as compared to the HCs." (PMID 36275702, 2022). "In fact, from the group comparison of COVID-19 vs. non-COVID-19, the authors identified 14 specific inflammatory proteins that can be related to SARS-CoV-2 infection, namely CXCL5, CXCL10, CXCL11, Gal-9, IL-18, IL-18R1, IFNγ, LIF-R, MCP-2, MCP-3, MERTK, MMP-1, PD-L1, and TNF." (PMID 35269564, 2022). "Levels of IL-1β were not affected, while, in contrast, serum IL-18 was increased in fatal COVID-19 cases." (PMID 35386707, 2022).
COVID-19 (continued). "As expected, significantly increased activation of pro-inflammatory cytokines (IL-1α, IL-2Ra, IL-6, IL-8, and IL-18) in fatal COVID-19 compared to non-fatal COVID-19 sera was measured." (PMID 35386707, 2022). "Our data show that the levels of these IL-1α, IL-1β IL-6 and IL-18 cytokines are significantly lower in severe COVID-19 survivors than in non-survivors." (PMID 36142255, 2022). "Neither IL-1RA nor IL-18 cytokines correlated with CRP when all COVID-19 patients were analysed or when the moderate and severe groups were separated (not shown)." (PMID 35663992, 2022). "Patients infected with COVID-19 have high amounts of IL1-β, IFN-γ, IP-10, IL-18, and MCP-1." (PMID 36160152, 2022). "SOTRs with COVID-19 have higher plasma levels of cytokines such as IFN-λ1, IFN-γ, IL-15, IL-18 IL-1RA, IL-6, MCP-2, and TNF-α as compared to healthy controls, and the levels of GM-CSF, IL-15, IL-6, IL-8, and IL-10 were associated with disease severity in SOTRs." (PMID 35075453, 2022). "The levels of IP-10, IL-15, IL-18, and TNF-α were exclusively increased in SOTRs with COVID-19." (PMID 35075453, 2022). "Interestingly, in asymptomatic carriers with COVID-19 the function of MAIT remain unchanged and upon E.coli stimulation or IL-12/IL-18, convalescent patients restored their functions." (PMID 35159352, 2022). "In addition, IL-1β, IL-4, IL-6, IL-18, IL-35, PGE2, and TXA2 levels in moderate and severe COVID-19 patients were significantly higher (p < 0.001) than in healthy controls." (PMID 36298501, 2022). "In serum of patients with severe COVID-19, the levels of IL-6, MIG, TNF-α, IL-8, IL-18 and IP-10 were higher than in the healthy controls (–G), while in moderate disease only the levels of IL-18, IL-8 and IP-10 were higher." (PMID 34539644, 2021). "Comparative proteomics identified statistically robust overexpression of several inflammatory cytokines, specifically IL6, IL18, CCL7, CXCL10, and CXCL11, which could be targeted to prevent untoward immune-inflammatory effects in COVID-19 patients." (PMID 35145507, 2021). "Some patients with severe COVID-19 experience cytokine release syndrome (CRS) or a cytokine storm—elevated levels of hyperactivated immune cells—and circulating pro-inflammatory cytokines, including interleukin (IL)-1β and IL-18." (PMID 34360684, 2021). "IL18, on the other hand, is one of the most important cytokines in macrophage activation syndrome, which has not been thoroughly studied in COVID-19." (PMID 35145507, 2021). "Ferritin, D-dimer, CRP, NLR, cytokine (IL-18 and IL-10), and cytokine receptor (IL-6, IL1-Ra, and sCD25) test results combined with clinical data can contribute to the early identification of critical COVID-19 patients." (PMID 34422145, 2021). "The fact that high levels of anthranilic acid predict the maintenance of high levels of IL10 and IL18 suggests (but does not prove) that the kynurenine pathway has an immunomodulatory impact on COVID-19 pathogenesis." (PMID 33707411, 2021). "Cytokines IL-18 and IL-33 were higher and IL-1β was lower in COVID-19 non-ICU patients versus controls (FDR < 0.1 or < 0.05)." (PMID 34960684, 2021). "IL-18 is a potential discriminator between AOSD and COVID-19 and may significantly predict active AOSD." (PMID 34367188, 2021). "Recent published studies in adult populations have reported that elevated levels of inflammatory cytokines levels such as TNF-α, IL-1β, IL-6, IL-10, IL-17, IL-18, IFN-γ are seen in active COVID-19 individuals compared to seropositive individuals and healthy controls." (PMID 33813138, 2021). "Indeed, levels of IL-18, a cytokine also known as IFN-γ-inducing factor, were significantly lower in critical COVID-19 than in MAS patients." (PMID 34226537, 2021). "Interleukin-18 (IL-18), a proinflammatory cytokine belonging to the IL-1 family, is elevated in both MAS and COVID-19 patients, and its level is known to correlate with the severity of COVID-19 symptoms." (PMID 33823154, 2021).
COVID-19 (continued). "A recent study has shown that male COVID-19 patients had higher circulating concentrations of cytokines such as IL-8 and IL-18, as well as a greater abundance of non-classical monocytes." (PMID 34434199, 2021). "The serum levels of IL-18 were significantly higher in the COVID-19 patients with MAS compared with COVID-19 patients without MAS and were associated with disease severity and poor clinical outcome in COVID-19 patients." (PMID 33823154, 2021). "Besides, IL-18 showed the highest discriminating ability between AOSD and COVID-19 in the ROC analysis of the putative markers." (PMID 34367188, 2021). "Currently, to our knowledge, no experimental evidence concerning the role of interleukin-18 in COVID-19 exists." (PMID 34911594, 2021). "In addition, IL-18 showed the highest discriminating ability between AOSD and COVID-19 in the ROC analysis of the putative markers." (PMID 34948117, 2021). "Upon stimulation with IL-12/IL-18, the percentage of Granzyme B (p = 0.007), IFN-γ (p = 0.008), TNF-α (p < 0.001) and Perforin (p = 0.03) expressing MAIT cells was significantly lower in COVID-19 patients compared to control uninfected individuals." (PMID 34238985, 2021). "The higher levels of Caspase-1 p20 and IL-18 indicated more severe symptoms and worse prognosis in patients with COVID-19, suggesting that NLRP3 inflammasome is not only activated but also plays a key role in COVID-19 progression." (PMID 34150848, 2021). "Our data suggest that blocking IL-1R7 could represent a potential therapeutic strategy to specifically modulate IL-18 signaling and may warrant further investigation into its clinical potential for treating IL-18-mediated diseases, including MAS and COVID-19." (PMID 33823154, 2021). "In COVID-19 patients, high serum levels of IL-12 and IL-18 have been described, further supporting the idea that MAIT cell decline in peripheral blood in COVID-19 patients may, at least partly, result from chronic cytokine exposure in vivo." (PMID 33546489, 2021). "Although the fold change of IL-18 in patients with AOSD was significantly higher than patients with severe COVID-19 (fold change: 594.00 vs 2.17), there was no statistical comparability." (PMID 33552062, 2020). "No appreciable changes were observed in IL-12p40, IL-18, or IL-1A in COVID-19-(+) plasma samples versus controls." (PMID 33245731, 2020). "There was also a trend toward higher IL-18 in the severe COVID-19 group compared with the sepsis group; however, this was not significant after multiple comparisons correction (adjusted P < 0.1)." (PMID 32706339, 2020). "This duality may partly explain why IL-18 alone did not differentiate between patients who developed COVID-19 and those who did not at specific time points." (PMID 40332340, 2025). "In this study, interestingly, mild/asymptomatic COVID-19+ pregnant women exhibited significantly elevated levels of proinflammatory cytokines/chemokines such as INF-α2, INF-γ, MCP-1, IL-6, IL-12p70, IL-17A, IL-18, IL-23, and IL-33, and the anti-inflammatory cytokine IL-10." (PMID 40303405, 2025). "Because plasmacytoid dendritic cells (pDCs) are the major source of IFN-α/β, IL-12, and IL-18 production, reduced expression of these cytokines aligns with previous studies showing reduced pDC function and defective MHC-II-dependent antigen presentation in COVID-19 patients." (PMID 38389037, 2024). "Notably, two post-infection vaccinations reduced the mean levels of IL-18 to the levels observed in individuals without COVID-19." (PMID 38316833, 2024). "For this, we have measured the expression of the different players implicated in the NLRP3 inflammasome pathway including NLRP3, CASP-1, ASC, IL-1β and IL-18 in whole blood of severe COVID-19 patients treated or not with 50,000 IU cholecalciferol once per week for 2–3 weeks during their stay at ICU." (PMID 38748756, 2024).